NEK9 (NIMA related kinase 9)
Diseases named in the same sentence as NEK9 in open-access papers (continued):
Sharing a sentence is not in itself a finding about the gene and the disease.
osteosarcoma (1 paper, 2014). A usually aggressive malignant bone-forming mesenchymal neoplasm, predominantly affecting adolescents and young adults. "To validate NEK9 as a RSR protein, we examined for phosphorylation of H2AX Ser139 (γH2AX), an early marker for DNA damage, following NEK9 knockdown in U2OS human osteosarcoma cells." (PMID 25217585, 2014).
Sepsis (1 paper, 2022). Sepsis is defined as life-threatening organ dysfunction caused by a dysregulated host response to infection. "This study revealed the involvement of NEKs, including NEK9, in inflammatory pathways, reporting their up-regulation in sepsis and highlighting their role as potential therapeutic targets in sepsis-derived ARDS." (PMID 36077551, 2022).
tauopathy (1 paper, 2021). Neurodegenerative disorders involving deposition of abnormal tau protein isoforms (tau proteins) in neurons and glial cells in the brain. "NEK9 was found to be differentially expressed in a tauopathy mouse model." (PMID 33589615, 2021).
uterine corpus endometrial carcinoma (1 paper, 2023). A endometrial carcinoma (disease) that involves the body of uterus. "This is further supported by GEPIA data, as uterine corpus endometrial carcinoma has the lowest tumor:normal tissue expression ratios of NEK7 and NEK9." (PMID 37046733, 2023).
cancer (15 papers, 2012 to 2025). A tumor composed of atypical neoplastic, often pleomorphic cells that invade other tissues. "Correspondingly, misregulation of NEKs can cause aberrant cell proliferation, and overexpression of several NEKs, including NEK6, NEK7, and NEK9, is associated with multiple cancers and cardiac hypertrophy." (PMID 37099601, 2023). "Although the role of NEK9 in mitosis involves cytoskeletal reorganization, the effects of NEK9 on cancer cell progression and motility have rarely been investigated." (PMID 37443302, 2023). "NEK9 is known to play a role in spindle assembly and in the control of centrosome separation, but the consequences of NEK9 targeting in cancer cells remain to be elucidated." (PMID 33664869, 2021). "The findings contained herein reveal that a number of off‐target effects of dabrafenib, such as NEK9 and CDK16, are inhibited at clinically achievable doses and that this likely contributes to its efficacy, particularly in cancers that lack BRAF mutations." (PMID 29112787, 2018). "NEK9 expression has been recently studied in relation to carcinogenesis and tumor progression, but its oncogenic role remains controversial as evidence of both anti- and pro-tumoral effects in different types of cancers have been reported." (PMID 36611072, 2023). "Furthermore, depletion of NEK9 results in inhibition of cell-cycle progression and proliferation of cancer cells." (PMID 36266340, 2022). "Indeed, a study has shown that Nek9 is responsible for gemcitabine sensitivity in cancer cells, where depletion of this kinase sensitizes cells to replication stress and reduces recovery, clearly implicating Nek9 in cancer cell survival signals." (PMID 35409400, 2022). "Thus, our study is the first to systemically investigate the effects of NEK9 on cell motility, which considerably extends current understanding of the role of NEK9 in cancer." (PMID 33500736, 2021). "Currently, little is known about the roles of NEK9 in cancer 26-31." (PMID 33500736, 2021). "Our studies identified NEK9 and CDK16 as two dabrafenib‐specific kinase targets and provide evidence that inhibition of NEK9 and CDK16 may underlie the greater effectiveness of this drug against NRAS‐ and KRAS‐mutant cancer cells." (PMID 29112787, 2018). "Given its critical roles in cell division and potential involvement in cancer progression, NEK9 represents an attractive target for drug development, offering therapeutic benefits by disrupting mitotic spindle formation and potentially inhibiting cancer cell migration and metastasis." (PMID 41154634, 2025). "Upregulation of NEK9 expression is also correlated with advanced tumor stages and reduced overall survival, indicating that NEK9 might serve as a prognostic marker in various cancers." (PMID 41154634, 2025). "Notably, one of the targets of miR-520f-3p, NEK9, is implicated in the phosphorylation of ARHGEF2, which, in turn, activates RhoA, promoting enhanced cell motility and facilitating both local and distant cancer cell spread." (PMID 39456519, 2024). "In this context, NEK9 functions as an effector of the interleukin-6 (IL-6)/STAT3 signaling pathway, which contributes to cancer metastasis." (PMID 41154634, 2025). "In the present study, NEK9 increased the total quantity and phosphorylation level of CTTN, which directly regulated cytoskeletal reorganization necessary for cancer cell movement." (PMID 37443302, 2023). "It was recently reported that quercetin inhibits a panel of kinases including NEK4, NEK9, and ABL1 in cancer cells." (PMID 27602754, 2016). "CDK5R2, NEK9, PRKCA, PXK and STK11 have significant effects on growth of cancer cells in all cancer cell lines." (PMID 22761558, 2012). "Though NEK9 is involved in primary cilia formation by acting as an autophagy adaptor for myosin heavy chain 9 non-muscle isoform IIA (MYH9IIA), a growing body of evidence suggests that it is also involved in several cellular processes related to cancer." (PMID 41154634, 2025).
cancer (continued). "Taken together, these findings have suggested that the aberrant expression of NEK9 is frequently observed in various cancers and is potentially a negative prognostic indicator." (PMID 36611072, 2023). "NEK9-medidated ARHGEF2 phosphorylation contributes to increased cell movement by inducing direct transformation of inactive RhoA to the active state to enable local invasiveness and distant metastasis of cancer cells." (PMID 33500736, 2021). "In cell‐based studies of NRAS‐ and KRAS‐mutant cancer cells, dabrafenib inhibited the NEK9 target CHK1, whereas vemurafenib did not." (PMID 29112787, 2018). "It is likely that NEK9 and CDK16 inhibition may contribute to the activity of dabrafenib, perhaps suggesting utility of this drug in other, non‐BRAF‐mutant cancers." (PMID 29112787, 2018). "In summary, we have identified dabrafenib as a potent inhibitor of NEK9 and CDK16, and our studies suggest that inhibition of these kinases may have activity against cancers that do not harbor BRAF mutations." (PMID 29112787, 2018). "A link between the cell cycle effects of NEK9 silencing and CDK4 suppression was suggested by pharmacological studies in which the CDK4 inhibitors palbociclib and ribociclib also induced a G1‐phase cell cycle arrest and senescence in the NRAS‐ and KRAS‐mutant cancer cell lines." (PMID 29112787, 2018). "In the present study, a simultaneous increase in the expression levels of NEK9, TRIM28 and CTTN was found in metastatic GC lesions compared with paired non-cancerous tissues and primary cancer lesions." (PMID 37443302, 2023). "A simultaneous increase in the expression levels of NEK9, TRIM28 and CTTN was found in metastatic GC lesions compared with paired non-cancerous tissues and primary cancer lesions via IHC and Multiplex IHC." (PMID 37443302, 2023).
tumor (14 papers, 2018 to 2026). "Clinically, NEK4 mutations were significantly associated with tumor site (P=0.02), NEK9 with tobacco exposure (P=0.01), and NEK10 with improved overall survival (P=0.01)." (PMID 41716219, 2026). "Interestingly, our findings indicated that a high NEK9 expression level was associated with a tumor size of over 60 mm and with an M stage." (PMID 36611072, 2023). "qRT-PCR analysis of NEK9 expression in 22 STAD tissue samples revealed that the relative expression levels were significantly higher than those in adjacent non-tumour tissues (P = 0.0473)." (PMID 38706902, 2024). "Generally, EAC tissues expressed significantly higher NEK3 and NEK9 as compared to normal esophageal epithelial cells, predominantly located in cytosol in both normal and tumor cells for NEK3 and NEK7." (PMID 37835513, 2023). "In particular, we observed that tumours with hypermethylated tgdDMR in the NEK9 promoter showed low NEK9 expression in both cell lines (ELMER, emp." (PMID 37558831, 2023). "Additionally, our study suggests that NEK9 plays a major role in tumour immunity and is therefore a potential biomarker for predicting both the disease prognosis and the efficacy of immunotherapy in patients with STAD." (PMID 38706902, 2024). "Considering that NEK9 is a centrosome binding protein during mitosis, a large tumor volume could be affected by a high mitotic activity." (PMID 36611072, 2023). "However, for the Nek9 silent group, tumor cells lack the Nek9 effect on regulating cell mitosis key points, can cause tumor cell of appreciation, and further promote the development of illness." (PMID 35935324, 2022). "To further investigate the role of NEK9 in STAD, we performed preliminary experiments to verify the differential expression of the gene in the tumour tissue and its correlation with immune cell markers." (PMID 38706902, 2024). "Nonetheless, the KMPlot data suggest potential avenues for exploring the tumor-suppressive qualities of NEK6, NEK7, and NEK9 in kidney renal cell carcinoma." (PMID 37046733, 2023). "Despite the known regulatory of NEK9, EG5 and microtubule acetylation in mitotic events, few studies have investigated the prognostic significance of these factors in different tumor types." (PMID 36611072, 2023). "By contrast, NEK1, NEK7, and NEK9 expression showed no obvious trend with the tumour grade." (PMID 38706902, 2024). "However, the role and mechanism of Nek9 in tumor cells have not been clearly described." (PMID 35935324, 2022).
skeletal dysplasia (2 papers, 2021 to 2022). Any Mendelian diseases that affects growth and development of the skeleton. "Therefore, the skeletal dysplasia observed in NEK9-related diseases is probably due to mitotic dysregulation resulting from the loss of NEK9 kinase activity, rather than impaired ciliogenesis." (PMID 34078910, 2021). "The same keywords were used in PubMed (covering time to August 2022), and three publications were found containing eight cases of skeletal dysplasia; only six cases have been identified with pathogenic mutations in the NEK9 gene, and genetic analysis was not carried out in another two cases." (PMID 36712877, 2022).
infection (1 paper, 2022). The state of being infected such as from the introduction of a foreign agent such as serum, vaccine, antigenic substance or organism. "The significant down-regulation of NEK9 [Q8TD19] observed in our study in the previously infected group lies well in line with the fact that none of our study participants underwent a severe disease course, indicating a protective residue of infection-acquired immunity." (PMID 36077551, 2022).
neurological disorder (1 paper, 2023). "For the neurological disorder-associated proteins SPG20 and NEK9 as well as the co-chaperone BAG2, these alterations were confirmed by immunoblotting for biotinylated proximity partners of APEX2-SEC13 and -SEC16A in TECPR2 WT and MUT cells." (PMID 36797266, 2023).
NEK9 also shares sentences with these, for which no sentence is quoted: Akinesia (1 paper); arthrogryposis, Perthes disease, and upward gaze palsy (1); cervical cancer (1); chronic myeloid leukemia (1); hepatocellular carcinoma (1); lymph node metastasis (1); microcephaly (1); non-small cell lung carcinoma (1); psychiatric diseases (1); testis cancer (1).